NTNG1 (netrin G1)
Diseases named in the same sentence as NTNG1 in open-access papers (continued):
Sharing a sentence is not in itself a finding about the gene and the disease.
Hyperglycemia (1 paper, 2017). An increased concentration of glucose in the blood. "Decreased expression of axon guidance pathway genes, Robo1, Ntn1, Ntng1, Nrp1, and Efnb3 in NSCs exposed to hyperglycemia was suggestive that miRNAs could target and deregulate the axonal guidance pathway as predicted by the pathway analysis." (PMID 28798665, 2017).
kidney cancer (1 paper, 2020). Primary or metastatic malignant neoplasm involving the kidney. "This may indicate that the carcinogenic mechanism of NTN1 and NTNG1 in pan-kidney cancers is related to promoter methylation." (PMID 32251318, 2020).
lymph node metastasis (1 paper, 2021). "In terms of lymph node metastasis, differential expression of NEGR1, NTNG1, XPNPEP2, CD109, OPCML, and PRND had statistical significance in the groups of N0 and N1." (PMID 34737762, 2021).
mood disturbance (1 paper, 2025). "The minor C allele of rs12028323, located at the PRMT6 (ENSG00000198890) and NTNG1 (ENSG00000162631) intergenic region, was associated with mood disturbance." (PMID 40440257, 2025).
Obesity (1 paper, 2024). Accumulation of substantial excess body fat. "A total of 12 significant SNPs associated with BMI were identified, of which 7 SNPs were also significantly associated with obesity, including rs1337406 (WLS), rs673612 (NTNG1), rs4449107 (FAM84A), rs9820485 (STAG1), rs73247924 (CCKAR), rs2083069 (ACADSB), and rs4942190 (DNAJC15)." (PMID 38807991, 2024).
pancreatic ductal adenocarcinoma (1 paper, 2022). An infiltrating adenocarcinoma that arises from the epithelial cells of the pancreas. "Netrin G1 (NetG1) expression on CAFs can suppress the cytotoxic function of NK cells and support the survival of cancer cells in nutrient-deprived environments and is thus linked to a poor prognosis in cancers such as pancreatic ductal adenocarcinoma." (PMID 36010899, 2022).
sarcoma (1 paper, 2019). A usually aggressive malignant neoplasm of the soft tissue or bone. "Netrin-G1 is only found in vertebrates and was first discovered in mice, where its gene, NTNG1, encodes for six isoforms formed by alternative splicing, regulated by the DNA/RNA-binding protein FUS (mutations in fused in sarcoma)." (PMID 30923634, 2019).
tumor (18 papers, 2020 to 2025). "Knockdown of Netrin G1 in tumor-associated fibroblasts in PDAC has been shown to reduce the presence of immuno-suppressive factors." (PMID 38099290, 2023). "A study of more than 10,000 samples across more than 30 tumour types found NTNG1 to have the highest mutation rate in the netrin family observing NTNG1 fusion transcripts in multiple cancers, including breast, lung and skin." (PMID 36045381, 2022). "In pancreatic ductal models, the high expression of the glutamatergic pre-synaptic protein netrin G1 (NetG1) in CAFs is also linked to their ability to inhibit NK cell-mediated killing of tumor cells." (PMID 36338519, 2022). "For instance, elevated expression of the glutamatergic presynaptic protein Netrin G1 in CAFs upregulates glutamate, glutamine, and cytokine expression, sustaining tumor cell viability through direct cell-cell interactions or activation of the Netrin G1/Netrin-G-Ligand-1 signaling pathway." (PMID 40861469, 2025). "This suggests that reducing Netrin G1 expression may activate NK cells, facilitating to create a less immunosuppressive tumor microenvironment and inhibiting PDAC progression." (PMID 38099290, 2023). "Both in vivo and in vitro studies have revealed that treatment with anti- Netrin G1 monoclonal antibodies effectively inhibits tumor formation, indicating that Netrin G1 may be a potential target for PDAC therapy." (PMID 38099290, 2023). "Silencing NTNG1 enhanced cisplatin effects in vivo, decreasing tumor volume/mass." (PMID 34277602, 2021). "Highly expressed NTN3, NTN5, and NTNG1 are correlated and sensitive to these three drugs, suggesting that the netrin family may be involved in tumor metabolism." (PMID 32251318, 2020). "We not only reveal the important role of the netrin family in the development of endocrine-related tumors and sex hormones targeting organ tumors, but suggest that NTNG1 and NTNG2 may be potential tumor diagnostic markers and treatment targets that warrant future in-depth systematic research." (PMID 32251318, 2020). "Recent studies have shown that Netrin G1 (NetG1) is the promoter of PDAC tumorigenesis in CAFs-related TME, and NetG1+CAFs stimulate immunosuppressive response and promote tumor progression through NetG1-mediated effects on glutamate/glutamine metabolism." (PMID 35965504, 2022). "In terms of tumor stage, differential expression of NEGR1, NTNG1, XPNPEP2, CD109, and PRND had statistical significance in all tumor stage groups." (PMID 34737762, 2021). "According to the Expression Atlas, the hypoxia-associated molecules CALB1, DDAH1, GAP43 and GPR37, as well as the tumor markers ART3, ENOL2 and FMOD and the tumor promoter NTNG1, are typically expressed in hematopoietic stem cells." (PMID 32466393, 2020). "However, it is important to note that the expression of IL15, a crucial factor in activating NK cells and enhancing the anti-tumor activity of CD8+ T cells, is significantly higher in tumor cells compared to Netrin G1." (PMID 38099290, 2023). "In SKOV3/DDP tumors, silencing NTNG1 did not inhibit the tumor; smaller tumors were detected in group shNTNG1 + CDDP compared with group shNC + CDDP (p = 0.021, p = 0.009)." (PMID 34277602, 2021). "In SKOV3 tumors, overexpression of NTNG1 did not affect the tumor; tumor volume and mass in group NTNG1 + CDDP were greater than those in group NC + CDDP (p = 0.030, p = 0.029)." (PMID 34277602, 2021). "Additionally, the participation of NTNG1 and NTNG2 in various cancers shows their potential for use as new tumor markers and therapeutic targets." (PMID 32251318, 2020). "The high expression of NTN1, NTN3, and NTNG1 is also sensitive to MS-275 (HDAC inhibitor), RG-108 (DNA methyltransferase inhibitor), and CUDC-101 (HDAC inhibitor, EGFR inhibitor, and HER2 inhibitor), which inhibit tumor by affecting epigenesis." (PMID 32251318, 2020).
tumor (continued). "She showed that the desmoplastic ECM sustains the expression of Netrin G1 in PDAC CAFs while tumor adjacent fibroblasts cultured in “normal” ECM do not express this protein." (PMID 33088423, 2020).
cancer (11 papers, 2015 to 2025). A tumor composed of atypical neoplastic, often pleomorphic cells that invade other tissues. "The hot spot mutation R238C/H of NTNG1 was detected in three patients with three cancers (COAD, STAD, and UCEC), and R238C was predicted as damaging in VEST3 and REVEL algorithms." (PMID 32251318, 2020). "Netrin G1 (NTNG1) is known for its role in glutamate and glutamine synthesis by CAFs, which is further taken up by cancer cells to expedite their energy needs." (PMID 36793444, 2023). "For NTNG1, as reported, hypermethylated regions were frequently detected in cancers, implying its potential function for CRC resistance and why there was no detection of this gene." (PMID 35774610, 2022). "Category- or stage-adjusted analyses demonstrated that the association between the NTNG1 level and prognosis occurred in type II or FIGO III/IV cancer." (PMID 34277602, 2021). "Clinical data indicated that patients with a low NTNG1 level in cancer tissues had longer PFI and PFS and that cancers exhibiting a low NTNG1 level were sensitive to cisplatin." (PMID 34277602, 2021). "Overall, the data demonstrated that a high level of NTNG1 in cancer tissues indicated poorer therapeutic responses and outcomes." (PMID 34277602, 2021). "The NTNG1 level was higher in resistant cancers compared with sensitive cancers (0.0124 ± 0.0021 vs. 0.0056 ± 0.0009, p = 0.005); the cutoff value was 0.0066." (PMID 34277602, 2021). "Here we find that the expression or methylation of NTNG1 and NTNG2 is associated with survival and other clinical parameters of more than 10 types of cancer." (PMID 32251318, 2020). "An unexpected finding in this study was the identification of the potential cancer biological significance of NTNG1 and NTNG2." (PMID 32251318, 2020). "It is worth noting that the mutations and potential mirRNA targeting of NTNG1 and NTNG2 in cancer exhibit rates that are much higher than those predicted for NTN1 and NTN4." (PMID 32251318, 2020). "Although some functions of NTNG1 have been investigated, the potential role and regulation of NTNG1 isoforms in cancer have still to be uncovered." (PMID 30923634, 2019). "Semaphorin 3A and Netrin-G1 could promote PDAC progression through their effects on cancer cells and immune cells." (PMID 40777309, 2025). "Patients with a high NTNG1 level in cancer tissues had shorter PFS [median: 11.0 (95% CI 8.9–13.0) vs. 25.0 (95% CI: 17.1–32.9) months, p = 0.010] and PFI [median: 5.0 (95% CI: 2.7–7.3) vs. 20.0 (95% CI: 13.9–26.1) months, p = 0.021], compared with those with a low level." (PMID 34277602, 2021). "Because high expression of NTN3 and NTNG1 is sensitive to these compounds, we can speculate that NTN3 and NTNG1 may be involved in the mesenchymal state of cancer." (PMID 32251318, 2020). "In cancer studies with at least five mutations in members of netrin genes, UCEC patients were one of the two highest among the cancers associated with the netrin family mutations, with most mutations in NTNG1." (PMID 32251318, 2020). "Category- or stage-adjusted analyses demonstrated that the correlation between a high NTNG1 level and poorer prognosis occurred only in type II or FIGO III/IV cancers." (PMID 34277602, 2021). "Adjusted analyses showed that the correlation between the high NTNG1 level and the poorer prognosis was observed in type II and FIGO III/IV cancers." (PMID 34277602, 2021).
neurological disorders (4 papers, 2013 to 2023). "It has also been reported that NTNG1 is associated with nervous system disease." (PMID 36980855, 2023). "Therefore, we speculate that NTNG2 and NTNG1 may play a role in neurological disorders." (PMID 34814929, 2021).
infection (1 paper, 2021). The state of being infected such as from the introduction of a foreign agent such as serum, vaccine, antigenic substance or organism. "We then obtained whole-cell voltage-clamp recordings from uninfected Ntng1+ and Ntng1- cells located away from the infection site." (PMID 34913870, 2021).
neurodegenerative disease (1 paper, 2025). A disorder of the central nervous system characterized by gradual and progressive loss of neural tissue and neurologic function. "Among the affected genes were APOE (apolipoprotein E), SEMA3C (semaphorin 3C), and NTNG1 (netrin G1), which have established roles in energy regulation and neurodegenerative disease." (PMID 41009961, 2025).
NTNG1 also shares sentences with these, for which no sentence is quoted: Intellectual disability (3 papers); cocaine dependence (2); adenocarcinoma (1); apraxia (1); Ataxia (1); atherosclerosis (1); autism spectrum disorder (1); Azoospermia (1); brain disorder (1); Cognitive impairment (1); developmental delay (1); Dravet syndrome (1); gastric cancer (1); glioma (1); iron deficiency (1); liposarcoma (1); lung adenocarcinoma (1); lung squamous cell carcinoma (1); malignant glioma (1); neurodevelopmental disorder (1); Parkinson disease (1); psychiatric disorder (1); renal carcinoma (1); round cell liposarcoma (1); spinocerebellar ataxia type 1 (1); type 2 diabetes (1).